RAB17 (RAB17, member RAS oncogene family)
Description:
The small GTPases Rab are key regulators of intracellular membrane trafficking, from the formation of transport vesicles to their fusion with membranes. Rabs cycle between an inactive GDP-bound form and an active GTP-bound form that is able to recruit to membranes different set of downstream effectors directly responsible for vesicle formation, movement, tethering and fusion (By similarity). RAB17 is involved in transcytosis, the directed movement of endocytosed material through the cell and its exocytosis from the plasma membrane at the opposite side. Mainly observed in epithelial cells, transcytosis mediates for instance, the transcellular transport of immunoglobulins from the basolateral surface to the apical surface. Most probably controls membrane trafficking through apical recycling endosomes in a post-endocytic step of transcytosis. Required for melanosome transport and release from melanocytes, it also regulates dendrite and dendritic spine development (By similarity). May also play a role in cell migration.
Tractability: Antibody: its Gene Ontology location is reachable by antibodies, with medium confidence. PROTAC: ubiquitination databases record sites on it; its protein half-life has been measured.
Gene: Protein-coding gene on chromosome 2 (237,574,322 to 237,601,623, reverse strand). Ensembl gene ENSG00000124839.
Subcellular location: Recycling endosome membrane; Melanosome; Cell projection, dendrite
Subcellular location (Human Protein Atlas): Vesicles
Pathways (Reactome):
Metabolism of proteins: RAB geranylgeranylation
Gene Ontology:
Molecular function: GDP binding; GTPase activity; protein binding; G protein activity; GTP binding
Biological process: cilium assembly; endocytic recycling; establishment of melanosome localization; filopodium assembly; immunoglobulin transcytosis in epithelial cells mediated by polymeric immunoglobulin receptor; melanosome transport; regulation of dendrite development; regulation of filopodium assembly; regulation of synapse assembly; transcytosis; anterograde dendritic transport; plasma membrane bounded cell projection assembly
Cellular component: endocytic vesicle; extracellular exosome; apical plasma membrane; basolateral plasma membrane; dendrite; early endosome; melanosome; neuronal cell body; plasma membrane; recycling endosome; recycling endosome membrane; cytoplasmic vesicle; dendrite cytoplasm; glutamatergic synapse; postsynapse
Genetic constraint (gnomAD): Loss-of-function variants: 16 observed, 20.04 expected, observed/expected ratio (o/e) 0.8, 90% interval 0.54 to 1.21. The upper end of that interval is the gene's LOEUF score, 1.21, which puts it in group 5 of 6, group 1 being the genes least tolerant of losing a copy. Missense variants: 262 observed, 276.56 expected, observed/expected ratio (o/e) 0.95, 90% interval 0.86 to 1.05. Synonymous variants: 110 observed, 115.94 expected, observed/expected ratio (o/e) 0.95, 90% interval 0.81 to 1.11.
Homologues: Orthologues: chimpanzee RAB17 (98% identical), mouse Rab17 (75% identical), rat Rab17 (75% identical), dog RAB17 (72% identical), guinea pig RAB17 (72% identical), macaque RAB17 (70% identical), pig RAB17 (59% identical). Paralogues in human: RAB5A (44% identical), RAB5C (44% identical), RAB5B (42% identical), RAB21 (39% identical), RAB26 (39% identical), RAB11B (37% identical), RAB1A (37% identical), RAB2A (37% identical), RAB11A (37% identical), RAB14 (37% identical), RAB37 (37% identical), RAB4B (37% identical), and 56 more.
Diseases named in the same sentence as RAB17 in open-access papers:
RAB17 is named in the same sentence as 20 diseases in open-access papers, as found by Europe PMC text mining. Sharing a sentence is not in itself a finding about the gene and the disease. The quoted sentences say what the papers report.
breast carcinoma (4 papers, 2017 to 2024). "We have previously shown that reduced Rab17 mRNA levels are associated with invasive migration of breast cancer cells." (PMID 28062852, 2017). "Consistent with our previous results, we found that low levels of Rab17 expression in breast tumours was strongly associated with poor overall patient survival (P<0.0001), and this was statistically significant in all breast cancer intrinsic subtypes, with the exception of the HER-enriched subtype." (PMID 28062852, 2017). "Previous studies have also shown that ERK2 suppresses RAB17 levels to promote breast cancer invasion." (PMID 39242574, 2024). "We labelled control and Rab17-knockdown MDA-MB-231 breast cancer cells with light-isotope and heavy-isotope SILAC amino acids, respectively (forward experiment), and with heavy-isotope and light-isotope amino acids, respectively (reverse experiment)." (PMID 28062852, 2017). "We, therefore, provoked breast cancer cell invasiveness by knocking down Rab17 or Vamp8 and tested the requirement for NRP2 in this." (PMID 28062852, 2017). "Our data, indicating the likelihood that Rab17 exerts its anti-invasive effects by maintaining Vamp8 levels, prompted us to investigate the relationship between Vamp8 and invasive pathology in breast cancer." (PMID 28062852, 2017). "Furthermore, we have shown that Rab17 levels must be suppressed for ERK2 to drive breast cancer invasiveness." (PMID 28062852, 2017). "Our identification of Vamp8 as an interactor of Rab17 and the fact that Vamp8 was downregulated in Rab17-depleted cells prompted us to determine whether Vamp8 contributes to the ability of Rab17 to function as a suppressor of breast cancer cell invasiveness." (PMID 28062852, 2017). "In silico analysis of breast cancer clinical datasets showed that KLK6 expression inversely correlates with RAB26, RAB17, and RAB30." (PMID 30980596, 2019). "In addition, reduced RAB17 promotes tumor progression by activating the ERK2 pathway in hepatocellular carcinoma and breast cancer." (PMID 39242574, 2024).
melanoma (4 papers, 2012 to 2025). A malignant, usually aggressive tumor composed of atypical, neoplastic melanocytes. "Rab17 siRNA knockdown in melanoma cells inhibited filopodia formation and led to a quantitative increase in the melanosome concentration at the cell periphery." (PMID 36829566, 2023). "RAB17 expression is regulated by MITF in mammalian cell lines (melanomas) and melanocytes with RAB17 knockdown have reduced filopodia formation, leading to impaired melanosome transfer." (PMID 22937744, 2012). "Rab17 knockdown did not inhibit melanosome maturation or movement, but it caused the accumulation of melanin inside melanoma cells." (PMID 36829566, 2023). "In addition to Rab27a, other Rab proteins such as Rab3a, Rab8, and Rab17 are involved in melanosome transport and distribution, including in melanoma cells, playing an important function in the transfer of melanin from melanocyte dendrites to keratinocytes." (PMID 33072757, 2020). "Despite being involved in melanosome transport, RAB17 also enhances melanoma growth in vivo." (PMID 33072757, 2020). "In particular, the activation of small GTPases such as CDC42, RAB17, RAC1, and RAB27A, which regulate cytoskeletal dynamics, is thought to contribute to melanoma progression and metastasis." (PMID 40594379, 2025).
ovarian carcinoma (4 papers, 2017 to 2024). A malignant neoplasm originating from the surface ovarian epithelium. "The downregulated gene RAB17 is associated with the increase in drug resistance in ovarian cancer and the promotion of the proliferation of cancer cells." (PMID 38891594, 2024). "Moreover, RAB17 knockdown increases the sensitivity of ovarian cancer cells to paclitaxel, inhibits proliferation, and leads to G1 phase arrest in the ovarian cancer cell cycle." (PMID 39242574, 2024). "Notably, circ_0000714 worked as a miR-370-3p sponge to regulate the expression of RAB17 in ovarian cancer cells." (PMID 38152652, 2023). "Survival of ovarian cancer patients was also associated with low Rab17 expression (P<0.0001), but we were unable to demonstrate any correlation between Rab17 levels in lung or gastric cancers (data not shown)." (PMID 28062852, 2017). "However, studies have shown that RAB17 is highly expressed in ovarian cancer cells." (PMID 39242574, 2024). "Moreover, RAB17 expression was upregulated in PTX-resistant A2780 ovarian cancer cells." (PMID 38152652, 2023). "In conclusion, circ_0000714 targeted miR-370-3p/RAB17 axis and activated CDK6/RB signaling pathway, leading to reduction of paclitaxel resistance in ovarian cancer." (PMID 38152652, 2023).
hepatocellular carcinoma (3 papers, 2021 to 2024). A malignant tumor that arises from hepatocytes. "Moreover, reduced levels of RAB17 have been reported to be associated with increased invasiveness of hepatocellular carcinoma." (PMID 39242574, 2024). "For example, Rab17 was decreased in hepatocellular carcinoma (HCC) and overexpression of Rab17 inhibited the tumorigenic properties of HCC cells." (PMID 33718142, 2021). "Recently, RAB17 has been identified as a tumor suppressor gene and low expression of RAB17 promotes the tumorigenesis via activation of the ERK pathway in hepatocellular carcinoma." (PMID 33461557, 2021).
endometrial carcinoma (2 papers, 2024 to 2025). A malignant tumor arising from the epithelium that lines the cavity of the uterine body. "Studies have indicated that RAB17 expression levels are associated with tumor malignancy, and RAB17 is more highly expressed in endometrial cancer (EC) tissues than in peritumoral tissues." (PMID 39242574, 2024).
head and neck squamous cell carcinoma (1 paper, 2025). A squamous cell carcinoma that arises from any of the following anatomic sites: lip and oral cavity, nasal cavity, paranasal sinuses, pharynx, larynx, and salivary glands. "TCGA analysis revealed that RAB17 was significantly upregulated in head and neck squamous cell carcinoma (HNSC) tissues compared to normal samples." (PMID 41213908, 2025).
Hypoglycemia (1 paper, 2024). A decreased concentration of glucose in the blood. "Because hypoglycemia increased RAB17 expression in EC cells, the role of a low-glucose in EC ferroptosis and tumor progression by regulating the RAB17-TFRC axis was further investigated by treating EC cells with low-glucose or high-glucose medium for 72 h." (PMID 39242574, 2024). "Because hypoglycemia is a common biological feature that promotes EC progression, the present study investigated whether RAB17 is altered under hypoglycemic conditions." (PMID 39242574, 2024).
lung carcinoma (1 paper, 2024). "The high expression of TBC1D7, a GAP for Rab17, was found in lung cancer tissues, which can significantly drive the development of lung cancer cells and was correlated with poor prognosis of patients." (PMID 39439452, 2024).
renal carcinoma (1 paper, 2013). A carcinoma arising from the epithelium of the renal parenchyma or the renal pelvis. "The IHC staining results confirmed the correlations between LGALS8, RAB17 and EpCAM and survival of renal carcinoma patients treated with sunitinib, while CD9 failed to achieve significant discriminatory potential." (PMID 23555683, 2013).
tumor (10 papers, 2013 to 2025). "RAB17 functions as a tumor suppressor, and its loss contributes to malignant phenotypes and elevated ferroptosis resistance via the NRF2-GPX4 axis." (PMID 41213908, 2025). "Mechanistically, LMO4 promotes tumor cell proliferation and migration by downregulating RAB17 via ubiquitin-mediated proteasomal degradation." (PMID 41213908, 2025). "Because EC is a relatively nutrient-deprived tumor with a low energy supply, the role of RAB17 in EC cells was investigated in hypoglycemic conditions." (PMID 39242574, 2024). "RAB17 overexpression significantly promoted tumor progression, as evidenced by accelerated tumor growth and a significant increase in tumor weight." (PMID 39242574, 2024). "Our analysis showed that all ERGs, except RAB17, had different expression levels between tumor and normal tissues." (PMID 37853449, 2023). "As expected, RAB17 knockdown significantly inhibited tumor progression." (PMID 39242574, 2024). "In addition, Prussian blue staining was performed to qualitatively measure the tumor iron levels, which that the intratumor iron levels were significantly lower in the high RAB17 expression group compared to the control group." (PMID 39242574, 2024). "Lastly, to promote MHC loading of tumor neoantigen in APCs after EV capture, an interesting recycling regulator Rab17 (shown to prevent presentation of AB derived self-antigens) could be targeted to promote tumor-specific immune destruction." (PMID 35320943, 2022). "Suppression of Rab17 levels through the activation of ERK2 signalling is likely to represent a key event in loss of the last vestiges of epithelial polarity, which allows tumours to invade and metastasise." (PMID 28062852, 2017). "Moreover, RAB17 expression was strongly correlated with tumor stage, histological grade, time of last pregnancy, erb-b2 receptor tyrosine kinase 2 (ERBB2) expression, estrogen receptor (ER) levels, progesterone receptor (PR) levels, and the Ki67 index in patients with EC." (PMID 39242574, 2024). "RAB17 (Ras-related protein Rab-17), a member of the RAB GTPase family, regulates intracellular trafficking and contributes to tumor development." (PMID 41213908, 2025). "Together, these results indicate that RAB17 suppresses EMT and invasive behavior in OSCC cells, further supporting its tumor-suppressive role." (PMID 41213908, 2025). "To validate RAB17 modulation by LMO4 in vivo, we analyzed tumor lysates by western blotting." (PMID 41213908, 2025). "Thus, Rab17 and Vamp8-dependent sequestration of NRP2 within the endosomes of tumour cells is likely to represent a remnant of the transcytotic system that still acts to suppress basement membrane disruption and the DCIS to IDC transition." (PMID 28062852, 2017). "Therefore, we particularly focused on sunitinib resistance and performed immunohistochemical experiments on tumor samples to validate the discriminatory potential of four new candidate biomarkers, LGALS8, RAB17, EpCAM, and CD9." (PMID 23555683, 2013).
cancer (6 papers, 2017 to 2025). A tumor composed of atypical neoplastic, often pleomorphic cells that invade other tissues. "The available database information concerning Rab17 and its interactors is insufficient to infer potential effectors and pathways through which this GTPase acts to suppress cancer invasiveness and progression." (PMID 28062852, 2017). "In various cancers, RAB17 acts context-dependently: it is inhibited by ERK2 (Extracellular Signal-Regulated Kinase 2) to facilitate breast cancer cell migration, suppresses hepatocellular carcinoma progression, and contributes to paclitaxel resistance in ovarian cancer." (PMID 41213908, 2025). "The expression and role of RAB17 have been extensively characterized in a variety of cancer tissues; however, the expression and function of RAB17 in EC are unknown." (PMID 39242574, 2024). "Previous studies have shown that RAB10, RAB11A, RAB17, and RAB25 could promote cell proliferation in different cancers." (PMID 35154286, 2022). "RAB17 gene, full name is member RAS oncogene family, which is a cancer- and immunity-related gene." (PMID 32849807, 2020).
neurological disorders (1 paper, 2024). "Among them, although mutations of other RAB family proteins have been linked to neurological disorders, RAB17 is an epithelial cell–specific GTPase and is expressed at a very low level in the central nervous system (GTExPortal, gtexportal.org)." (PMID 37943610, 2024).
RAB17 also shares sentences with these, for which no sentence is quoted: adenocarcinoma (1 paper); angiosarcoma (1); breast tumours (1); cervical cancer (1); diabetic foot ulcers (1); gastric cancer (1); invasive carcinoma (1); lymphoma (1).